ABCG2 (ATP binding cassette subfamily G member 2 (JR blood group))
Diseases named in the same sentence as ABCG2 in open-access papers (continued):
Sharing a sentence is not in itself a finding about the gene and the disease.
cancer (continued). "It has also been suggested that the inhibition of this kinase and the connected PI3K/Akt signaling pathway, activated in many human tumors, might be an important drug target for reducing ABCG2-related cancer drug resistance." (PMID 37887994, 2023). "Our findings demonstrated that at sub-micromolar concentrations, furmonertinib sensitized multidrug-resistant cancer cells overexpressing ABCB1 or ABCG2, as well as cells with ectopic expression of human ABCB1 or ABCG2, to cytotoxic drugs in a concentration-dependent manner." (PMID 37762275, 2023). "Moreover, polyoxypregnane compounds isolated from MTE have been reported to overcome ABCB1‐ or ABCG2‐mediated multidrug resistance in cancer cells." (PMID 36756719, 2023). "In this study, we investigated the susceptibility of HS-173 to efflux mediated by the multidrug efflux transporters ABCB1 and ABCG2, which are two of the most well-known ATP-binding cassette (ABC) transporters associated with the development of cancer multidrug resistance (MDR)." (PMID 37048130, 2023). "ABCG2 was an important gene involved in chemotherapy resistance of most cancer cells." (PMID 37621132, 2023). "This contradicts the suggestion that ABCG2 protects cancer cells from harmful substances and prolongs the life of cancer cells; however, this could be connected with some other properties of ABCG2." (PMID 37445716, 2023). "Furthermore, ABCG2 has been identified as a potential marker for stem cells and a novel target for cancer therapy." (PMID 37511298, 2023). "Furthermore, we provide evidence that imperatorin achieves this reversal of ABCG2-mediated MDR by antagonizing the drug efflux function of ABCG2, all while leaving its protein expression level unaffected within these cancer cells." (PMID 38004460, 2023). "ABCG2 is expressed on a lower level in most cancers and shows a protective effect." (PMID 36555598, 2022). "Similarly, IM restored the sensitivity of ABCG2-expressing cancer cells to topotecan via increasing the intracellular accumulation of this chemotherapeutic agent." (PMID 35327403, 2022). "These include ALDH1, ABCG2, CD44, CD133, NANOG, and SRY-box transcription factor 2 (SOX2), all of which have been linked to chemoresistance in a number of first line anti-cancer therapies—for example, axitinib is an oral, potent, small molecule ATP-competitive multitarget tyrosine kinase inhibitor." (PMID 36338714, 2022). "ABCB1, ABCC1, and ABCG2 are essential for developing cancer chemotherapy resistance (MDR)." (PMID 35897925, 2022). "p75ICD was weak in stage II, while a progressive increase in the number of p75ICD-positive cells was noticeable from stages III to IVb, where a further increase in the single cell expression level was found in cells with enlarged nuclei, most of them also positive for the ABCG2 cancer marker." (PMID 35681602, 2022). "Consequently, the overexpression of ABCG2 found in many human cancers is thought to be a major contributor to the development of multidrug resistance (MDR), which is a serious obstacle in cancer treatment." (PMID 35665065, 2022). "Our results revealed that P-gp overexpression, but not expression of ABCG2, was associated with reduced cancer cell susceptibility to ensartinib." (PMID 35565470, 2022). "ABCG2 and tubulin are mechanisms by which cancer cells resist treatment." (PMID 36232899, 2022). "ABCG2, as a marker for cancer stem cells, plays a major role in multidrug resistance in NSCLC." (PMID 35684095, 2022). "Similarly, imatinib, nilotinib, dasatinib, and danusertib were found to be the substrates of ABCG2/BCRP transporter that increases the efflux of these TKIs from cancer cells." (PMID 35327403, 2022). "supported the hypothesis that the Oxaliplatin resistance in CRC correlated with the ABCG2 over-expression in a subset of cancer stem cells." (PMID 36585626, 2022).
cancer (continued). "We discovered that at low, sub-toxic concentrations, hydroxygenkwanin could selectively re-sensitize ABCG2-overexpressing multidrug-resistant cancer cells to cytotoxic anticancer drugs." (PMID 36361555, 2022). "As the low level of Pgp and ABCG2 expression in cancer cells resistant to the studied drugs was observed, we propose that other mechanisms of MDR may be more important in STS." (PMID 35328603, 2022). "PFKFB3 knockdown and PFK158 treatment in a H1048 SCLC cancer stem cell-enriched mouse xenograft model showed significant reduction in tumor growth and weight with reduced expression of cancer stem cell markers, ABCG2, and YAP/TAZ." (PMID 35804016, 2022). "Whether ABCG2 participates in the pathogenesis or pharmacokinetics in all types of cancer through certain common molecular mechanisms remains to be clarified." (PMID 36555598, 2022). "ABC proteins, such as ABCB1, ABCB5, ABCC1, ABCC2, ABCC4, ABCC5, and ABCG2, have been identified as being involved in irinotecan and SN-38 transport out of the cytosol to reduce its intracellular concentration and efficacy in cancer cells." (PMID 35885025, 2022). "Subcellular localization of ABCG2 transporter plays a protective role in normal gallbladder epithelial cells; cellular accumulation of ABCG2 in poorly differentiated cancer might correlate with the activation of PI3K signaling pathways." (PMID 36158120, 2022). "Moreover, natural compounds such as flavonoids, terpenoids, and chalcones were found to modulate the function of ABCG2, whereas genistein, curcumin, and epigallocatechin gallate (EGCG) were found to modulate the expression of ABCG2 in cancer cell lines." (PMID 36361555, 2022). "Following promising inhibition of cancer stemness and ABCG2 levels, an impact of PFKFB3 depletion by PFK158 or its genetic KD effect on migration and invasion was examined on H1048 and H1882 cells through invasion and migration assay and EMT protein expression analysis by immunoblot." (PMID 35804016, 2022). "Interestingly, the results show that ABCG2 is negatively correlated to most types of cancer concerning RNAss and DNAss." (PMID 36555598, 2022). "In breast cancer high level of ABCG2 expression is observed in stem cancer cells." (PMID 35328603, 2022). "ABCG2 is an ATP‐binding cassette (ABC) transporter G2 that has been connected with regulation of the intracellular accumulation of porphyrin derivatives in cancer cells and consequently a modulator of the efficacy of PDT." (PMID 32737955, 2022). "The fact that methoxy groups are favorable for the action of chalcones on ABCG2 was also performed for four naphthochalcones (Compounds 58–61), which were synthesized to evaluate their effect on cancer cell growth on five different entities, using MTT analysis (2,5-diphenyl-2H-tetrazolium bromide)." (PMID 36232899, 2022). "Further, to understand the role of YAP/TAZ in PFKFB3 mediated regression of cancer stemness and ABCG2 expression, XMU-MP-1 (an inhibitor that activates YAP/TAZ via MST1/2 inhibition) used to activate YAP/TAZ in H1048CSC and H1882CSC cells and when treated with PFK158." (PMID 35804016, 2022). "ABCG2 (also called BCRP) decreases the transfer of drugs to cancer cells." (PMID 36232899, 2022). "ABCG2 functions as a transporter to regulate the efflux of drugs in cancer cells." (PMID 35566676, 2022). "ABCG2 is known for its role in PpIX export but whether it is involved in 5-ALA mediated PpIX selective accumulation in cancer cells is unclear." (PMID 35887311, 2022). "Moreover, p75ICD co-expression was found in cancer cells with weak (hashtag) and strong (arrow) ABCG2 expression in the cytosol." (PMID 35681602, 2022). "The mRNA expression level of ABCG2 showed a significant difference among spheres and drug-resistant cancer cell lines compared with their corresponding adherent cancer cell lines in six types of cancer." (PMID 36555598, 2022).
cancer (continued). "The significantly different expression levels of the ABCG2 gene between drug-resistance groups and the adherent groups were explored in this article for the first time, which implied that ABCG2 acts multi-functionally in the different types of drug-resistant cancer cells." (PMID 36555598, 2022). "Here, we demonstrate that post-hypoxia SPm (hox)+/ABCG2+ CSCs of seven cancer cell lines including SCC-25 exhibit a TSD phenotype against BCG and Mtb-m18b that involve bystander apoptosiss and therefore could be of potential use to eliminate CSCs." (PMID 36248858, 2022). "Identifying ABCG2 inhibitors could help discover extraordinary curative strategies for carcinoma remediation." (PMID 35224675, 2022). "The MDR to chemotherapeutic drugs in cancer cells is mediated through a mechanism involving P-glycoprotein (P-gp, or MDR1), multidrug resistance-associated protein 1 (MRP1, or ABCC1), or breast cancer resistance protein (BCRP, or ABCG2)." (PMID 34771642, 2021). "ABCG2 is a transporter contributing to multidrug resistance of cancer cells." (PMID 34282134, 2021). "Albeit previously isolated from multidrug resistant cancer cells, the expression and distribution pattern of ABCG2 in normal cells and tissues substantiates its other important physiological role, which is protecting the organism as a first line of defense against environmental toxins." (PMID 33670777, 2021). "Taken together, our study revealed that the drug transport mediated by ABCB1 or ABCG2 represents a novel mechanism for acquired resistance to citarinostat in human cancer cells; therefore, combination therapies will need to be tested to overcome this clinical problem in the future." (PMID 33807514, 2021). "It has also been reported that ABCG2 transports anti-cancer agents such as Imatinib from cells." (PMID 33562088, 2021). "In cancer therapeutics, a strategy of ABCG2 inhibition could be employed to increase bioavailability of chemotherapy agents and overcome cancer cell resistance." (PMID 34572902, 2021). "ABCG2-Q141K has been shown to diminish drug efflux and/or to increase sensitivity to various anti-cancer drugs, including methotrexate, numerous TKIs (gefitinib, erlotinib, lapatinib, imatinib, dasatinib, nilotinib), and the topoisomerase I inhibitor indolocarbazole." (PMID 33801813, 2021). "Indeed, nuciferine abates the expression of ABCB1 and ABCG2, improving the anti-cancer activity of paclitaxel in vitro and in vivo." (PMID 34575983, 2021). "Since gedatolisib had limit effect to inhibit ABCB1- and ABCG2-overexpression cancer cells, the potential mechanisms could be related with the upregulation of ABC transporter expression level." (PMID 33593355, 2021). "Therefore, PFC has promise as a therapeutic to overcome ABCG2-mediated MDR to improve the efficiency of cancer chemotherapy." (PMID 34830383, 2021). "In our study, we chose to test whether VKNG-1 could act as a chemosensitizing agent to the ABCG2-overexpressing MDR phenotype of cancer cells and explore the mechanism of ABCG2-mediated chemoresistance." (PMID 34572902, 2021). "In our data, GLRX was considered to regulate the cancer stem cell phenotype via non-canonical Wnt signaling pathways associated with RhoA and ABCG2 via Wnt5a and Wnt7b." (PMID 34794402, 2021). "Additionally, IHC staining in 46 EC samples and 26 control samples revealed significantly lower protein levels of ABCG2 and OSTβ in cancer tissue." (PMID 33917029, 2021). "Thus cancer MDR is often associated with overexpression of ABC transporters such as ABCB1, ABCG2 and ABCC1, which have been proved to mediate the efflux of structurally distinct chemotherapeutic agents." (PMID 34631561, 2021). "ABCG2 is ubiquitously expressed in normal tissues while overexpressed in various cancer cells." (PMID 33670777, 2021).
cancer (continued). "ABC transporter comprises ABCs (multidrug resistance-associated proteins (MRPs)), ABCB1 (P-glycoprotein/MDR1), and ABCG2 (BCRP/MXR/ABCP)) all were reported to be overexpressed in cancer developing the MDR." (PMID 34205602, 2021). "ABCG2 is frequently reported as a chemoresistance, as well as cancer stem cell-related marker." (PMID 34794402, 2021). "In addition to these cells constituting tissue barriers, ABCG2 is also expressed in various types of stem cells including hematopoietic stem cells, pluripotent stem cells, and cancer stem cells." (PMID 33801813, 2021). "As we characterized MLN7243 as a substrate of ABCG2, cancer cells may express higher level of ABCG2 protein upon MLN7243 treatment." (PMID 34336849, 2021). "Besides Q141K, some other frequent polymorphisms, such as V12M and Q126X, have been included in a limited number of clinical studies investigating the effect of ABCG2 SNPs on cancer chemotherapy and therapy-related toxicity." (PMID 33801813, 2021). "However, the effect of prolonged citarinostat exposure on the protein expression of ABCB1 and ABCG2 in cancer cells remains to be determined." (PMID 33807514, 2021). "Thus, our findings that the genetic interaction between SLC31A1 and ABCG2 polymorphisms was associated with clinical outcomes of NSCLC patients receiving platinum-based chemotherapy may have important implications for the pharmacoethnicity of platinating agents in cancer chemotherapy." (PMID 33531973, 2021). "Some reports indicate that ABCG2 is expressed uniquely in cancer stem cells, a minority of the total cell population; thus, ABCG2’s role may be obscured in bulk tumor sequencing." (PMID 34049503, 2021). "Chalcone 1, a natural product isolated from the root of Glycyrrhiza inflata, could inhibit the drug transport function of ABCG2 and reverse ABCG2-mediated multidrug resistance in human multidrug-resistant cancer cell lines." (PMID 33307878, 2021). "Moreover, accumulating evidence indicates that ABCG2 plays a particularly important role in regulating the cellular accumulation of porphyrin derivatives in cancer cells, thereby affecting the efficacy of photodynamic diagnosis (PDD) and PDT." (PMID 33670777, 2021). "Therefore, heme synthesis enzymes and ABCG2 play vital roles in regulating the cellular accumulation of PpIX in cancer." (PMID 33670777, 2021). "In summary, as shown in schematic illustration, our study revealed the effect of ABCB1 and ABCG2 on the pharmacological impact of citarinostat, which may play an important role in the development of resistance to citarinostat in cancer cells." (PMID 33807514, 2021). "Therefore, Western blot analysis was performed to determine the GS-9973 mechanism on the ABCG2 protein expression in the parental and resistant cancer cells." (PMID 34326700, 2021). "Taken together, our findings reveal that TP-3654 is a selective, potent modulator of ABCG2 drug efflux function that may offer an additional combination therapy option for the treatment of multidrug-resistant cancers." (PMID 34502348, 2021). "Many inhibitors of ABCG2 have been reported to enhance the chemosensitivity of cancer cells." (PMID 34830383, 2021). "Therefore, more extensive studies to examine the role of ABCG2, especially in solid tumors, is warranted to provide a constructive picture of this pump’s role in cancer biology." (PMID 33670777, 2021). "These compounds chemosensitize cancer cells overexpressing ABCG2." (PMID 33469044, 2021). "The combination of M3814 and ABCG2 substrate drugs may allow additional benefit for cancer patients with high ABCG2 expression." (PMID 32477940, 2020). "Three ABC transporter proteins, P-glycoprotein (P-gp, MDR1, ABCB1), multidrug resistance protein 1 (MRP1, ABCC1), and breast cancer resistance protein (BCRP, ABCG2), have been shown to play a role in multidrug resistance of various types of cancers like OC, breast, lung, colon and others." (PMID 32257947, 2020).
cancer (continued). "Consequently, ABCB1 and ABCG2 remain a crucial therapeutic target for improving therapeutic outcomes in cancer patients undergoing chemotherapy." (PMID 31941029, 2020). "Interestingly, like nilotinib, sitravatinib is also a TKI that re-sensitizes ABCB1- and ABCG2-overexpressing cancer cells to chemotherapeutic drugs by modulating the drug efflux function of both drug transporters." (PMID 31941029, 2020). "Thus, we examined the effect of tivantinib on ABCG2 protein expression in both drug-selected cancer cells and gene transfected cells using Western blotting and immunofluorescent staining." (PMID 31940916, 2020). "Therefore, specific control of ABCG2 transporter expression in cancer cells alone would enhance the effects of anticancer drugs without increasing adverse events." (PMID 33333736, 2020). "Taken together, these results establish that overexpression of ABCG2 may contribute to MLN4924 drug resistance in multiple cancer cell lines." (PMID 32059437, 2020). "In addition, EC16-1/saporin induced apoptosis in parental and ABCB1- and ABCG2-overexpressing cancer cells." (PMID 32098067, 2020). "Additionally, there is a need to expand these studies from the usual ABCB1, ABCC1, and ABCG2, to encompass all the other transporters identified as dysregulated in cancer." (PMID 32587767, 2020). "Notably, previous studies have reported that certain TKIs can reverse multidrug resistance mediated by ABCB1 and ABCG2 in cancer cells by interacting strongly with these ABC drug transporters." (PMID 31941029, 2020). "Our findings suggest that the EC16-1/saporin combination could potentially be a novel therapeutic treatment in patients with parental or ABCB1- and ABCG2-positive drug-resistant cancers." (PMID 32098067, 2020). "Functionally, ABCB1 and ABCG2 work as efflux pumps, and are located in the lipid raft of specific cell lines, reducing the intracellular level of various antineoplastic agents accumulating in cancer cells." (PMID 32477943, 2020). "Notably, previous studies have demonstrated strong interactions between certain TKIs and ABCB1 and/or ABCG2, resulting in the resensitization of multidrug-resistant cancer cells overexpressing ABCB1 or ABCG2." (PMID 31941029, 2020). "That prior treatment may alter expression of ABCG2 in cancer cells is supported by our recently published data on CRC cell lines made resistant to SN-38 by steadily increasing the dose of SN-38." (PMID 32708825, 2020). "The ABCG2-mediated resistance to tivantinib may have clinical implications for patients using tivantinib for cancer treatment." (PMID 31940916, 2020). "The spectrum of anti-cancer drugs ABCG2 confers resistance to overlaps with that of ABCB1." (PMID 33066132, 2020). "Later, ABCG2 cDNA was cloned from the S1-M1-80 cancer cell line and termed MXR." (PMID 31940916, 2020). "Compared with control xenograft tumors, the mRNA levels of cancer stemness-related genes, including ABCG2, BMI1, NANOG, KLF4, and OCT4 were increased and the protein expression of ABCG2, Oct4, Bmi-1, and CD44 were also increased in HBx-expressing xenograft tumors." (PMID 32168902, 2020). "After determining the non-toxic concentration of AZ-628, we then studied whether AZ-628 can affect the MDR in cancer cells which overexpress wild-type or mutant ABCG2 proteins." (PMID 33364237, 2020). "Overexpression of ABCG2 can lead cancer cells resistant to various chemotherapeutic drugs." (PMID 32175279, 2020). "Therefore, it is important to uncover effective modulators to circumvent ABCG2-mediated MDR in cancers." (PMID 33364237, 2020). "The development of multidrug resistance (MDR) in cancer patients driven by the overexpression of ATP-binding cassette (ABC) transporter ABCB1 or ABCG2 in cancer cells presents one of the most daunting therapeutic complications for clinical scientists to resolve." (PMID 31941029, 2020). "The cancer cell lines have been found to differ substantially in ABCG2 promoter methylation." (PMID 33066132, 2020).